MTOR (mechanistic target of rapamycin kinase)
Diseases named in the same sentence as MTOR in open-access papers (continued):
Sharing a sentence is not in itself a finding about the gene and the disease.
tumor (continued). "To conclude, this study underscores the potential of Hh inhibitors, Vis and Cyc, to enhance trastuzumab’s anti-tumour activity via SMO-regression and AKT/mTOR pathway inactivation." (PMID 40426308, 2025). "Furthermore, mTOR inhibitors can directly suppress the proliferation of tumor cells, inhibit the growth of endothelial cells, and reduce their response to vascular endothelial growth factor, thereby suppressing angiogenesis and exerting an indirect anti-tumor effect." (PMID 40421010, 2025). "PTEN is a tumor suppressor which exerts tumor-suppressive functions, mainly by impairing the phosphoinositide 3-kinase (PI3)/AKT/mTOR pathway relevant for cell growth and survival through dephosphorylating the 3- position of phosphoinositides." (PMID 39851496, 2025). "Activation of CXCL12/CXCR4 triggers downstream signaling pathways, including the PI3K/AKT/mTOR and MAPK/ERK cascades, which promote tumor cell proliferation and survival." (PMID 40698080, 2025). "As a tumor suppressor, miR-10a-5p inhibits tumor progression by targeting the PI3K/Akt/mTOR pathway, thereby reducing cell proliferation and invasion." (PMID 39796267, 2025). "More importantly, the downstream effectors of the mTOR pathway, such as VEGF, and HIF-1α, which contribute to angiogenesis and tumor cell survival were also suppressed, leading to significant tumor inhibition following the combination treatment." (PMID 40604062, 2025). "In tumor cells, this AMPK-mediated mTOR inhibition limits proliferation by restricting energy and biosynthetic precursors." (PMID 41190142, 2025). "The tumor-inhibiting properties of silymarin stem from its ability to modulate many cell signaling pathways such as Bcl-2/Bax, PI3K/Akt/mTOR, STAT3, and MAPK pathway." (PMID 39836338, 2025). "Beyond innate tumor genetics, the tumor microenvironment (TME) plays a key role: uLMS often presents with a low lymphocytic infiltration phenotype, whereas the activation of PI3K/mTOR pathway leads to immune evasion." (PMID 41303434, 2025). "Paired tumor biopsies revealed treatment-induced modulation of the TME, including alterations in innate immune genes, adaptive immunity pathways, and mTOR signaling." (PMID 41584838, 2025). "Lycopene's anti‐inflammatory properties suppresses the tumor growth and development‐promoting pathways, such as the PI3K/Akt/mTOR pathway." (PMID 40661795, 2025). "Certain signaling pathways in tumor cells, such as the PI3K/Akt/mTOR pathways, regulate DNL activity." (PMID 40533802, 2025). "MSNs loaded with siRNA can target tumor cells and silence PI3K/AKT/mTOR pathway components and modulate autophagy." (PMID 40076496, 2025). "Superior MTA1-mediated anticancer effects of Gnetin C also included a downregulation of oncogenic/tumor-promoting ETS2, pAkt/Akt, Cyclin D1, p-mTOR/pS6K/p4EBP1 and AR signaling." (PMID 40077738, 2025). "It regulates key pathways such as AKT/mTOR, cytochrome c/caspase, and SGK1-FOXO3a-BNIP3, influencing tumor cell proliferation, metastasis, apoptosis, and autophagy." (PMID 40259338, 2025). "Western blot analysis revealed that, after interference with NR6A1 in the three tumor cell lines, AMPK was the least affected, and the total protein levels and serine phosphorylation (Ser2448) of mTOR were significantly decreased." (PMID 41219936, 2025). "The high-NOTCH2 expression group showed significant enrichment in multiple tumor-promoting pathways, including PI3K-AKT, TGF-β, MAPK, mTOR, and KEAP1-NFE2L2 signaling." (PMID 41200204, 2025). "By modulating critical pathways (e.g., AKT/mTOR, JAK/STAT, and NRF2) in tandem with Tregs, MDSCs, and fibroblasts, it dampens tumor progression while enhancing chemotherapy responsiveness." (PMID 40490812, 2025). "In non-small cell lung cancer, GPER1 can promote the activation of PI3K/AKT/mTOR signaling, induce SCD1 expression, and thereby prevent ferroptosis in tumor cells, facilitating tumor progression." (PMID 41407677, 2025).
tumor (continued). "CDH11 not only acts as an effector molecule but also influences tumor cell function by interfering with BCAA metabolism and activating the mTOR pathway." (PMID 39739317, 2025). "UBE2C was previously shown to promote tumor invasion and proliferation by activating protein kinase B/mammalian target of rapamycin (AKT/mTOR) pathway." (PMID 41081939, 2025). "We used flow cytometry to quantify the levels of p4E-BP1, a downstream effector of mTOR signaling, within CD45−CD98+ MC38 tumor cells, CD4+ T cells, and CD8+ T cells." (PMID 41160695, 2025). "They enhance immune cell activity, modulate key tumour-related signalling pathways (e.g., PI3K/AKT/mTOR, MAPK, NF-κB), and improve chemotherapy efficacy by sensitising tumour cells and reducing drug resistance and toxicity." (PMID 40649307, 2025). "Silencing TREM1 induces a shift from M2 to M1 polarization, reducing M2 markers and impairing tumor cell migration and invasion via suppression of the PI3K/AKT/mTOR pathway." (PMID 40764998, 2025). "The circRNA affects the PI3K/AKT/mTOR signaling pathway as well as the upregulation of SLC7A11, essential for tumor metabolism." (PMID 41081939, 2025). "POSTN secreted by tumor cells mainly directly binds to integrins, activates the MAPK/ERK and AKT/mTOR signaling pathways, and thereby promotes metastasis and proliferation." (PMID 41018265, 2025). "In summary, our research demonstrated that circ_0092278 is upregulated in PTC, and its overexpression promotes tumor cell proliferation, invasion, and migration by activating the PI3K/AKT/mTOR pathway." (PMID 40537911, 2025). "In contrast, in CRC models, APS induces autophagy in HCT116 tumor tissues and cells, inhibiting proliferation and migration through the PI3K/Akt/mTOR pathway." (PMID 40149916, 2025). "A growth factor that promotes angiogenesis, the formation of new blood vessels, VEGF, is often overexpressed in tumors due to activation of various pathways, including PI3K/AKT/mTOR and Ras/Raf/MEK/ERK, driving tumor growth and metastasis." (PMID 41050183, 2025). "By targeting key signaling pathways—PD-1/PD-L1, CTLA-4/CD28, JAK/STAT, PI3K/AKT/mTOR, and MAPK/ERK—it enhances T-cell activation and proliferation and regulates immune checkpoint expression, such as PD-L1 on tumor cells." (PMID 40563651, 2025). "Cancer‐associated fibroblasts (CAFs) secrete growth factors such as HGF, IGF‐1, FGF and TGF‐β, activating pathways like PI3K/Akt/mTOR and MAPK, which promote tumour proliferation, increase macromolecule synthesis, and lead to cell volume expansion." (PMID 40525649, 2025). "Rescue experiments indicated that MYB upregulation counteracted the tumor-suppressive effects of miRNA-195-5p and reactivated PI3K/AKT/mTOR signaling." (PMID 41141380, 2025). "In tumor cells, aberrant activation of PI3K, AKT, and mTOR, as well as the deletion of phosphatase and tensin homolog (PTEN), can promote tumorigenesis." (PMID 40507124, 2025). "METTL14 can inhibit tumor proliferation and invasion by modulating the PI3K/AKT/mTOR signaling pathway." (PMID 41312360, 2025). "These intermediates modulate several intracellular signaling pathways, such as HIF-1α, mTOR, and PI3K/Akt, ultimately influencing tumor cell responses to chemotherapy and targeted therapies." (PMID 40115255, 2025). "This was validated in a xenograft model whereby tumor growth rate was reduced, suggesting that resveratrol inhibits tumor growth and promotes survival in a mechanism involving reduced PI3K/Akt/mTOR pathway activation." (PMID 41226537, 2025). "Notch signaling enhances mTOR pathway activity by inducing the transcription of HES-1, a repressor of PTEN, a tumor suppressor that normally inhibits the PI3K/AKT/mTOR pathway." (PMID 40003637, 2025). "Through the activation of the mTOR signaling pathway and modulation of an immunosuppressive TME, this miRNA cluster promotes tumor survival and drug resistance." (PMID 41550951, 2025).
tumor (continued). "However, a meta-analysis of studies looking at mTOR inhibitors specifically demonstrated that monotherapy agents such as Temsirolimus were not able to achieve any significant tumor response—though it was able to afford some short-lived tumor control with a PFS of 1.86 months." (PMID 40868227, 2025). "The KD has also been shown to influence signaling pathways such as downregulating the PI3K/Akt/mTOR pathway and activating AMPK, which can inhibit tumor cell proliferation and survival." (PMID 40944231, 2025). "Western blot analysis exhibited that equimolar CBD: THC (2.5:2.5 μM) markedly reduced phosphorylation of PI3K, AKT, and mTOR, while increasing phosphorylation of PTEN, thereby reactivating tumor-suppressive signaling." (PMID 41472794, 2025). "Extensive research has demonstrated that Urolithin A can inhibit signaling pathways including mTOR, PI3K/Akt, and ERK in T cells, nerve cells, and tumor cells, highlighting its therapeutic potential in treating tumors and neurological disorders." (PMID 40723388, 2025). "These drugs target multiple crucial tumor development and progression processes, including PI3K/mTOR signaling, DNA replication, and apoptosis regulation." (PMID 40129974, 2025). "In vivo, AE attenuated tumor growth (p < 0.05), correlating with lncRNA D63785 downregulation and PI3K/Akt/mTOR dephosphorylation." (PMID 40756984, 2025). "CB‐839, a GLS inhibitor, enhances the tumoricidal activity of natural killer cells by blocking glutamine used by tumor cells, boosting glutamine availability in the TME, and activating the mTOR and c‐Myc signaling pathways." (PMID 40956032, 2025). "Consistent with the RNA-seq data, Western blotting confirmed the elevated mTOR signaling in RAC1A159V tumors in both in vitro culture and in vivo tumor experimental settings." (PMID 41160695, 2025). "In parallel, OVs can disrupt the cytoskeleton architecture of tumor cells by modulating signaling pathways such as Rho/ROCK and PI3K/Akt/mTOR, which regulate cytoskeletal dynamics." (PMID 40927720, 2025). "PTEN functions as a tumor suppressor by dephosphorylating PIP3, thereby preventing activation of the oncogenic PI3K/Akt/mTOR-signalling pathway." (PMID 40872585, 2025). "Moreover, metformin may improve tumor oxygenation by selectively killing hypoxic cells through the suppression of the mammalian target of rapamycin (mTOR) pathway and modulation of the unfolded protein response (UPR), both important for cell survival under hypoxic conditions." (PMID 40105683, 2025). "In tumours, the abnormal expression of the PI3K/Akt/mTOR pathway activates downstream signalling, such as the phosphorylation of 4E‐BP1, leading to the release of the eukaryotic translation initiation factor eIF4E and promoting protein translation." (PMID 40525649, 2025). "While ALK inhibitor treatment led to a reduction in phosphorylated AKT and the mTOR downstream target S6K1, AKT signaling was effectively reinduced following the cultivation of H2228 and H3122 tumor spheroids with CAF-CM." (PMID 40524253, 2025). "Subsequently, the PI3K/AKT/mTOR was identified as a downstream effector of the has‐circ‐0008234/miR‐338‐3p/ETS1 axis, contributing to enhanced tumor aggressiveness." (PMID 40740483, 2025). "Mechanistic studies revealed that β-lapachone inhibits cell proliferation, metastasis, glucose metabolism, tumor angiogenesis, and EMT by targeting AKT1 to inactivate the PI3K/AKT/mTOR pathway." (PMID 40051559, 2025). "Moderate ROS levels can promote tumor cell proliferation and serve as second messengers in growth factor activation through the PI3K/AKT/mTOR and MAPK/ERK signaling cascades." (PMID 39899624, 2025). "The impact of mTOR inhibitors on molecular markers such as p‐S6K1 and p‐4EBP1 in different tissues, including skin, peripheral blood mononuclear cells (PBMCs), and tumor biopsies, has been examined in a number of studies." (PMID 40717210, 2025).
tumor (continued). "In another study, glucose depletion in murine sarcoma cells was shown to inhibit mTOR activity, reduce glycolytic capacity, and decrease IFN‐γ production in T cells, collectively promoting tumor progression." (PMID 40365984, 2025). "Adiponectin, a key adipocytokine, plays a role as a tumor suppressor by phosphorylating AMPK, downregulating MAPK, JAK/STAT, mTOR, and Wnt/β‐catenin pathways, inhibiting metastases, and reversing epithelial‐mesenchymal transition." (PMID 40304310, 2025). "Transcriptomic analysis indicates that BCKDK downregulation alters multiple biological processes, including mTOR, ErbB, Hippo, and apoptosis signaling pathways, highlighting its critical role in RCC tumor progression." (PMID 40789057, 2025). "CS’s abundant expression of aspartyl-asparaginyl-β-hydroxylase (ASPH), which drives invasive tumor growth via Notch and PI3K/mTOR activation, opens opportunities for treatment in combination with standard Doxorubicin (DOX) chemotherapy." (PMID 40427168, 2025). "Tumor growth was monitored, and molecular analyses included RNA sequencing and immunofluorescence quantification of PI3K, AKT1, mTOR, ERBB2, BRAF, and MITF protein levels, and molecular docking simulations were performed." (PMID 40806647, 2025). "These compounds modulate key oncogenic pathways, such as PI3K/AKT/mTOR, NF-κB, and STAT3, to suppress tumor growth, induce apoptosis, and inhibit metastasis." (PMID 40667502, 2025). "Combinatorial approaches with mTOR or AKT inhibitors demonstrate additive effects, while integration with immune checkpoint blockade potentiates T cell-mediated tumor clearance." (PMID 40266213, 2025). "Elevated levels of activated mTOR (phosphorylated mTOR) are commonly found in CRC tissues, which correlate with advanced tumor stages characterized by the inhibition of apoptosis, heightened tumor aggressiveness, and diminished patient survival." (PMID 40500799, 2025). "At present, the autophagy pathways in tumor cells are relatively complex, with the AMPK/mTOR/p70S6K signaling pathway and the Beclin-1 signaling pathway being particularly relevant to autophagy in BC." (PMID 40688079, 2025). "Lactate regulates MDSC activation through the GPR81/mTOR/HIF-1α/STAT3 pathway, and blocking lactate production in tumor cells restores anti-tumor T cell responses." (PMID 40650086, 2025). "This was corroborated both in vitro and in vivo, where the combination of β-elemene and cisplatin yielded the most pronounced reduction in tumor burden and PI3K/AKT/mTOR phosphorylation." (PMID 41480385, 2025). "The activity of the mTOR pathway is regulated by the phosphoinositide 3-kinase PI3K-Akt pathway, which is also frequently aberrant in various neoplasms." (PMID 41375037, 2025). "The interferon response has also been shown to interact with PI3K/AKT/mTOR signaling to drive HCC proliferation and tumor cell migration." (PMID 41439936, 2025). "Tumor and myeloid cells compete with T cells for glucose in the TME, which impairs T cell function by suppressing Notch signaling and reducing mTOR activity and IFN-γ production, thus enabling tumor growth." (PMID 40092297, 2025). "For example, FBLN2 is a tumor suppressor gene in NSCLC that inhibits tumor cell survival, proliferation, and invasion through multiple mechanisms, including the suppression of the MAPK/ERK and PI3K/AKT/mTOR signaling pathways." (PMID 41469472, 2025). "According to research, brusatol and bruceine D activate the JNK /p38 MAPK signaling pathways while suppressing the activation of Stat3/NF-κB, PI3K/Akt/mTOR, and PI3K/Akt/NF-κB pathways, thereby inducing apoptosis in various tumor cells." (PMID 41156537, 2025). "The expression of p-mTOR, p-p70S6K, HSF1, and cyclin D1 is also decreased in tumor tissues, contributing to reduced proliferation, increased apoptosis, and inhibition of migration and invasion." (PMID 40572668, 2025).
tumor (continued). "ITZ has been demonstrated to elicit its antitumor effects by inhibiting tumor cells proliferation through multiple signaling pathways, including Wnt/β-catenin, Hedgehog, and PI3K/AKT/mTOR." (PMID 40697374, 2025). "UMAP distribution showed that AKT1 and ESR1 were primarily expressed in tumor cells, SRC and IL6 were concentrated in the Myeloid subpopulation, while MTOR and HIF1A exhibited a broader distribution across multiple cell types." (PMID 40746726, 2025). "Analysis of the database revealed that IL-6 was positively correlated with angiogenesis, tumor inflammatory signaling, apoptosis, Pentose/phosphate/pathway, PI3K/AKT/mTOR pathway, and P-53 pathway." (PMID 40040705, 2025). "The combined use of a PI3K inhibitor and anti‐Fibulin‐3 antibodies significantly inhibited tumor cell proliferation and growth, suggesting that future studies targeting the PI3K/Akt/mTOR pathway should consider combination therapies." (PMID 40904706, 2025). "The small-molecule inhibitor SBI-0206965 selectively inhibits ULK1 and synergizes with mTOR inhibitors to promote ULK1 degradation and enhance tumor cell apoptosis, outperforming chloroquine (CQ) in efficacy." (PMID 41009794, 2025). "Studies have demonstrated the potential activation of the mTOR pathway in BCAA metabolism, which is involved in tumor development." (PMID 39739317, 2025). "CircST3GAL6, as a tumor suppressor, also modulates autophagy-mediated proliferation, migration, and metastasis via the miR-300/FOXP2/Met/mTOR pathway." (PMID 40778324, 2025). "The PI3K/Akt/mTOR signaling pathway is a central regulator of cellular processes and is frequently dysregulated in HCC, driving tumor progression, metabolic reprogramming, and therapeutic resistance." (PMID 40943288, 2025). "scRNA-seq revealed compartment-specific target localization: AKT1/ESR1 in tumor cells, SRC/IL6 in myeloid cells, and MTOR/HIF1A across stromal compartments." (PMID 40746726, 2025). "Across tumor types, PTEN and PIK3CA showed frequent non-synonymous alterations, indicating shared drivers within the mTOR axis." (PMID 41300706, 2025). "Phosphatase and tensin homolog (PTEN) is a key tumor suppressor involved in controlling cellular proliferation and survival, mainly by modulating the PI3K/AKT/mTOR pathway." (PMID 41009024, 2025). "This is achieved by down-regulating the activation of the PI3K/AKT/mTOR signaling pathway, inhibiting the downstream vascular endothelial growth factor (VEGF) and VEGFR2, and enhancing tumor cell sensitivity to chemotherapeutic agents." (PMID 41281753, 2025). "mTOR is negatively regulated by AMPK, and AMPK inhibits mTOR activity by indirectly regulating TSC2 and TSC1 together to form tumor suppressor complexes." (PMID 39944825, 2025). "In both in vitro cell experiments and in vivo xenograft tumor models, CXCL3 overexpression led to elevated protein levels of PI3K, p-PI3K, AKT, p-AKT, mTOR, and p-mTOR compared to mock controls." (PMID 41259383, 2025). "The immune checkpoint blockade is capable of rescuing exhausted T cells by enhancing their glucose influx and glycolysis via mTOR signaling and Myc induction, which allows IFN-γ production and improves their effector anti-tumor function." (PMID 39851525, 2025). "By inhibiting calcium signaling, mTOR activity, and glycolysis, sodium citrate enhances CAR-T cell persistence and promotes the development of memory T cells, which improves their anti-tumor efficacy." (PMID 40165944, 2025). "Key signaling cascades, including PI3K/AKT/mTOR and MAPK, support tumor proliferation, survival, and resistance to apoptosis." (PMID 40227764, 2025). "When tested in in vivo studies, the combination of CBD (5 mg/kg) and DOX reduced tumor volume (p < 0.001, n = 4), increased the expression of BAX and cleaved caspase-3, and decreased Bcl2 and mTOR." (PMID 40006844, 2025). "SphK1 promotes tumor cell proliferation, migration, and angiogenesis by activating signaling pathways such as PI3K/AKT/mTOR and MAPK/ERK." (PMID 41234914, 2025).